GEMIN4 (gem nuclear organelle associated protein 4)
Description:
The SMN complex catalyzes the assembly of small nuclear ribonucleoproteins (snRNPs), the building blocks of the spliceosome, and thereby plays an important role in the splicing of cellular pre-mRNAs. Most spliceosomal snRNPs contain a common set of Sm proteins SNRPB, SNRPD1, SNRPD2, SNRPD3, SNRPE, SNRPF and SNRPG that assemble in a heptameric protein ring on the Sm site of the small nuclear RNA to form the core snRNP (Sm core). In the cytosol, the Sm proteins SNRPD1, SNRPD2, SNRPE, SNRPF and SNRPG are trapped in an inactive 6S pICln-Sm complex by the chaperone CLNS1A that controls the assembly of the core snRNP. To assemble core snRNPs, the SMN complex accepts the trapped 5Sm proteins from CLNS1A forming an intermediate. Binding of snRNA inside 5Sm triggers eviction of the SMN complex, thereby allowing binding of SNRPD3 and SNRPB to complete assembly of the core snRNP.
Synonyms: HHRF-1; DKFZP434B131; p97; DKFZP434D174; HC56; HCAP1; NEDMCR
Tractability: PROTAC: ubiquitination databases record sites on it; its protein half-life has been measured.
Gene: Protein-coding gene on chromosome 17 (744,421 to 753,999, reverse strand). Ensembl gene ENSG00000179409.
Subcellular location: Cytoplasm; Nucleus; Nucleus, nucleolus; Nucleus, gem
Subcellular location (Human Protein Atlas): Cytosol; Nuclear bodies
Pathways (Reactome):
Disease: SARS-CoV-2 modulates host translation machinery
Metabolism of RNA: snRNP Assembly
Gene Ontology:
Molecular function: protein binding; ribonucleoprotein complex binding
Biological process: spliceosomal snRNP assembly; rRNA processing
Cellular component: Cajal body; cytosol; extracellular exosome; membrane; nuclear body; nucleolus; SMN complex; SMN-Sm protein complex; cytoplasm; nucleoplasm; small nuclear ribonucleoprotein complex; Gemini of Cajal bodies; nucleus
Genetic constraint (gnomAD): Loss-of-function variants: 57 observed, 75.06 expected, observed/expected ratio (o/e) 0.76, 90% interval 0.61 to 0.95. The upper end of that interval is the gene's LOEUF score, 0.95, which puts it in group 4 of 6, group 1 being the genes least tolerant of losing a copy. Missense variants: 1,284 observed, 1,347.3 expected, observed/expected ratio (o/e) 0.95, 90% interval 0.91 to 1. Synonymous variants: 553 observed, 576.33 expected, observed/expected ratio (o/e) 0.96, 90% interval 0.89 to 1.03.
Homologues: Orthologues: chimpanzee GEMIN4 (98% identical), macaque GEMIN4 (96% identical), dog GEMIN4 (86% identical), pig GEMIN4 (84% identical), rabbit GEMIN4 (84% identical), guinea pig GEMIN4 (84% identical), mouse Gemin4 (82% identical), rat Gemin4 (81% identical), tropical clawed frog gemin4 (43% identical), zebrafish gemin4 (33% identical).